HSPB1 (heat shock protein family B (small) member 1)
Diseases named in the same sentence as HSPB1 in open-access papers (continued):
Sharing a sentence is not in itself a finding about the gene and the disease.
neuropathy (23 papers, 2012 to 2026). A disorder affecting the nervous system that manifests with pain, tingling, numbness, and/or muscle weakness. "While neuropathy-causing mutations in the ubiquitously expressed small heat shock protein HSPB1 account for a subset of axonal CMT cases, the mechanisms underlying the selective vulnerability of peripheral neurons remain poorly understood." (PMID 41677634, 2026). "HSPB1 is associated with multiple diseases, such as atherosclerosis, inflammation, neuropathy, and malignancy, via regulating cell apoptosis, proliferation, autophagy, and metastasis." (PMID 39071496, 2024). "This is reflected in the link of this network to muscular atrophy and Charcot Marie Tooth disease another neuropathy which is characterized by progressive muscular loss and genetic link to HSPB1." (PMID 35576218, 2022). "So far, little is known about the influence of neuropathy-linked mutations in HSPB1 and HSPB8 on the formation and dynamism of stress granules." (PMID 32323160, 2020). "Patients with HSPB8 mutations present with a very similar phenotype as patients with HSPB1-linked neuropathy, with the exception that thigh weakness, CNS involvement, and autosomal recessive transmission have not been observed." (PMID 32323160, 2020). "Our findings suggest that HSPB1 mutations result in two phenotypes of inherited neuropathies and extend the phenotypic spectrum of HSPB1‐related disorders." (PMID 29381233, 2018). "This specific HSPB1 mutation results in a severe neuropathy phenotype affecting exclusively the motor neurons of the peripheral nervous system." (PMID 28077174, 2017). "This study demonstrates in vitro drug screening models of inherited neuropathy resulting from mutations in the HSPB1 gene can be developed from patient-specific iPSCs." (PMID 28105056, 2016). "In this study, we explore the evolutionary history of four human sHSPs: HspB1, HspB3, HspB5, and HspB8, all known disease factors as mutant alleles have been found associated with various forms of neuropathies, myopathies, and with cataracts in the lens of the eye." (PMID 35678958, 2022). "Interestingly, in our case series, HSPB1 pathogenic variants were found in 3% of genetically determined neuropathies." (PMID 35330153, 2022). "The clinical phenotypes are very similar to the neuropathies caused by HSPB1 mutations." (PMID 32093037, 2020). "The p.P182L mutation was recently shown to increase the interaction of HSPB1 to the RNA-binding protein PCBP1, interfering with its ability to suppress the translation of its target genes—some which are known neuropathy genes." (PMID 32093037, 2020). "A detailed phenotype and natural history study of HSPB1 neuropathy is therefore required in order to inform the duration and outcome measures of any future trials." (PMID 27816334, 2017). "HSPB1 related neuropathies, however, are rare and any future prospective trial will require patients to be recruited from multiple centres in order for statistically significant changes in clinical and imaging outcome measures to be identified." (PMID 27816334, 2017). "Examples are treatment with HDAC6 inhibitors in HSPB1 mutant mice, restoring axonal transport defects, and treatment with curcumin improving outcome of neuropathy in MPZ mutant mice." (PMID 25025039, 2014). "Dominant mutations in HSPB1 are associated with CMT type 2F and distal hereditary motor neuropathy (dHMN); the S135F mutation leading to a higher affinity of HSPB1 for tubulin overstabilizing microtubules determines neuropathies affecting axonal transport." (PMID 36010576, 2022). "It has been reported that TBA treatment increases not only axonal transport and the number of moving mitochondria but also the level of acetylated α-tubulin in neuropathies of a Charcot-Marie-Tooth model that have been induced by mutant heat-shock protein gene (HSPB1)." (PMID 22937007, 2012). "Similarly, HSPB1 or HSPB8 have been described in neuropathies and/or myopathies." (PMID 35281256, 2022).
neuropathy (continued). "The development of transgenic mouse models of mutant HSPB1 neuropathy and the encouraging preclinical studies of HDAC6 inhibitors in HSPB1 and GARS neuropathy have highlighted the need for robust natural history with which to guide future trial design." (PMID 27816334, 2017). "Despite the well evaluated clinical phenotypes, the biochemical and functional characterization for most of these HSPB1 mutations is still missing, and the molecular mechanisms at the basis of HSPB1-related neuropathies are not straightforward." (PMID 35281256, 2022).
distal hereditary motor neuropathy (22 papers, 2005 to 2025). "So far disease causing mutations in HSPB1 have been associated with neurodegenerative diseases such as distal hereditary motor neuropathy, Charcot-Marie-Tooth disease and amyotrophic lateral sclerosis." (PMID 28077174, 2017). "This gene has been linked previously to neurodegeneration, as mutations in human HSPB1 cause some cases of Charcot-Marie-Tooth disease and distal hereditary motor neuropathy." (PMID 27152617, 2016). "In particular, about twenty mutants of HspB1 are associated with distal hereditary motor neuropathy and/or type II Charcot-Marie-Tooth disease." (PMID 25965061, 2015). "Following the detection of the first HSPB8 mutations in distal hereditary motor neuropathy (dHMN), discovered simultaneously with HSPB1 mutations as cause on another dHMN, mutations in HSPB8 have also been linked to Charcot–Marie–Tooth (CMT) disease and muscle disease." (PMID 40243504, 2025). "Mutations in the HSPB1 gene encoding Hsp27 are associated with motor neuropathies such as Charcot–Marie–Tooth disease and distal hereditary motor neuropathies, and overexpression of Hsp27 in an Alzheimer’s disease mouse model reduces amyloid-β plaques and improves spatial learning and memory." (PMID 40241479, 2025). "Interestingly mutation of glycine at position 34 to arginine in the NTR of HspB1 (equivalent to glycine at position 30 in DmHsp27) has been associated to distal hereditary motor neuropathies." (PMID 28520783, 2017). "Mutations in HSPB1 are one of the commonest causes of distal Hereditary Motor Neuropathy (dHMN)." (PMID 27816334, 2017). "Mutations in HSPB1 are reported in motor neuron diseases, including distal hereditary motor neuropathy type II (dHMN) and the axonal form of Charcot-Marie Tooth disease (CMT2), as well as in ALS." (PMID 38507480, 2024). "Similar to BAG3 and HSPB8, mutations in the genes coding for DNAJB2, HSPB1 and HSPB3 have been associated with distal hereditary motor neuropathy (dHMN), including Charcot–Marie–Tooth disease." (PMID 40757567, 2023). "Mutations in HSPB1 are known to cause Charcot-Marie-Tooth disease type 2F (CMT2F) and distal hereditary motor neuropathy (dHMN)." (PMID 36291591, 2022). "The first half of this paper will be focused on how mutations in HSPB1, HSPB3, and HSPB8 are linked to inherited peripheral neuropathies like Charcot-Marie-Tooth (CMT) disease and distal hereditary motor neuropathy (dHMN)." (PMID 32323160, 2020). "So far, 26 mutations (including 22 missense mutations) have been found in HSPB1 that are responsible for axonal Charcot-Marie-Tooth neuropathy (CMT2F), distal hereditary motor neuropathy (dHMN) and amyothropic lateral sclerosis (ALS)." (PMID 28077174, 2017). "Mutations in the HSPB1 gene encoding the small heat shock protein B1 are associated with an autosomal dominant, axonal form of Charcot–Marie–Tooth disease 2F (CMT2F) and distal hereditary motor neuropathy." (PMID 28828227, 2017). "Only a few HSPB1 mutations have previously been identified in families with CMT2F and families with distal hereditary motor neuropathy (HMN2B), and most of them are located in the α-crystallin domain." (PMID 22206013, 2011). "Mutant HSPB1 (heat shock protein family B member 1) can cause a group of length-dependent peripheral axonal neuropathy, including Charcot-Marie-Tooth disease type 2F (CMT2F) and distal hereditary motor neuropathy (dHMN)." (PMID 36291591, 2022). "Mutations of the gene encoding HSPB1 have been associated with different neuromuscular diseases; in particular, autosomal dominant hereditary distal axonal neuropathies, including Charcot Marie Tooth disease type 2 (CMT2) and distal hereditary motor neuropathy (dHMN)." (PMID 36233058, 2022). "Despite their multifunctionality and ubiquitous expression, mutations in HSPB1 and HSPB8 affect specifically the peripheral nervous system causing the axonal form of Charcot-Marie-Tooth neuropathy (CMT2) and/or distal hereditary motor neuropathy (dHMN)." (PMID 32323160, 2020).
glioblastoma (16 papers, 2015 to 2025). The most malignant astrocytic tumor (WHO grade IV). "Existing research indicates that HSPB1 may act as a potential oncogene in glioblastomas and is associated with poor prognosis in patients." (PMID 37723588, 2023). "Among them, Fli-1 signaling is associated with the occurrence of GBM and is highly expressed in radiotherapy- and temozolomide-resistant glioblastomas, and can regulate HSPB1 at the transcriptional level." (PMID 40149733, 2025). "A study regarding glioblastoma also showed that a knockdown of HSPB1 evidently induced ferroptosis and enhanced ACSL4 stability via reducing SUMOylation of ACSL4." (PMID 37509438, 2023). "Clinically, HSPB1 overexpression correlated with poor survival rate in both glioblastoma and brain low-grade glioma." (PMID 27711253, 2016). "Expression level of heat shock protein 27 (HSPB1/HSP27) discriminated glioblastoma presenting short (6 ± 4 months, n = 4) and long survival (43 ± 15 months, n = 4) (p = 0.00045)." (PMID 26108672, 2015). "Additionally, the friend leukemia integration 1 (Fli-1)-mediated upregulation of HSPB1 (HSP27) in glioblastoma cells was correlated with their resistance to temozolomide and radiation." (PMID 33806538, 2021). "Moreover, knockdown of HspB1 in-vitro induced apoptotic cell death, whereas HspB1 upregulation reduced apoptosis and enhanced tumorigenic potential in-vivo in glioblastoma multiforme." (PMID 32927696, 2020). "Using RNAseq quantification of different HSPs in GBMs obtained from the GDC TCGA glioblastoma cohort (n = 155) cbioportal we identified expression of HSPB1 to be highest in GBM." (PMID 32284788, 2020). "Recent research has shown that Rg5 inhibits glioblastoma progression by activating nuclear receptor subfamily 3 group C member 1 (NR3C1), thereby regulating heat shock protein family B member 1 (HSPB1) and nuclear receptor coactivator 4 (NCOA4)." (PMID 40552277, 2025). "NR3C1 can act as a direct target of ginsenoside Rg5 to regulate the expression levels of HSPB1 and NCOA4 and inhibit glioblastoma progression." (PMID 40995432, 2025). "Among them, HSPB1, also known as HSP27, a small heat shock protein, has been validated to inhibit ferroptosis cell death in HeLa cells, glioblastoma, esophageal squamous carcinoma and bladder cancer cells." (PMID 38041016, 2023). "It illustrates that targeted inhibition of Fli-1/HSPB1-mediates EMT and ECM remodeling signaling axes by genetic (shRNAs/siRNAs) inhibitors can regulate GBM phenotype and might provide novel therapeutic reagents for radio/TMZR glioblastoma." (PMID 32284788, 2020). "Moreover, higher RNA expression of HSPB1 was discovered in several other cancers, such as cervical and endocervical cancer (CESC), cholangiocarcinoma (CHOL), esophageal carcinoma (ESCA), glioblastoma (GBM), kidney renal papillary cell carcinoma (KIRP), and liver hepatocellular carcinoma (LIHC)." (PMID 37454220, 2023).
Charcot-Marie-Tooth disease (15 papers, 2013 to 2024). An inherited degenerative disorder involving the peripheral nerves. "For example, in the axonal form of Charcot-Marie-Tooth disease, HSPB1 mutants are associated to cause cell death due to cytoskeletal damage." (PMID 34429462, 2021). "For example, mutations in HSPB1, 3, and 8 are associated with Charcot-Marie-Tooth Disease and mutations in HSPB8 are also associated with hereditary spastic paraplegic neuropathy, two diseases associated with axonal degeneration." (PMID 33013325, 2020). "Mutations in HSPB1 have also been identified in patients with another neuropathy, Charcot-Marie-Tooth disease." (PMID 30398641, 2018). "Other studies have shown that several missense mutations in HSPB1 cause the peripheral neuropathy, Charcot-Marie-Tooth (CMT) disease, which is associated with nerve degeneration." (PMID 29048431, 2017). "In 2004 we found that mutations in HSPB1 cause a peripheral neuropathy called Charcot-Marie-Tooth disease (CMT)." (PMID 23826100, 2013). "According to reports, mutations in the HSPB1 gene have been associated with neurodegenerative diseases, including Charcot-Marie-Tooth disease (CMT) and late-onset amyotrophic lateral sclerosis (ALS)." (PMID 38809509, 2024).
melanoma (14 papers, 2012 to 2025). A malignant, usually aggressive tumor composed of atypical, neoplastic melanocytes. "In the investigation of underlying mechanisms, we found knock down of HSPB1 further increased the proportion of apoptotic cells in hyperthermic treated melanoma cells when compared with either single agent alone, and both agents leaded to cell cycle arrest at G0/G1 or G2/M phases." (PMID 27626679, 2016). "Validation using melanoma data from TIDE revealed that key CSS-associated molecules (CD24, HSPB1, SLC25A5) profoundly influenced immunotherapy outcomes." (PMID 40777020, 2025). "Another gene within the HSP family, HSPB1, was selected as a top marker that instead inhibits melanoma growth." (PMID 39763976, 2024). "For instance, the secretion of the C-terminal HSPB1 fragment has been found to inhibit the progression of melanoma cells." (PMID 39763976, 2024). "We concluded that hyperthermia combined with silencing of HSPB1 enhanced cell death and resulted in failure to thrive in melanoma cell lines, implying the potential clinical utility of hyperthermia in combination with HSPB1 inhibition in cancer treatment." (PMID 27626679, 2016). "We also showed that reduction of HSPB1 in both murine and human melanoma cells increased apoptosis and cell cycle changes." (PMID 27626679, 2016). "Here we present our data suggesting that silencing thermosensitive HSPB1 sensitized murine melanoma and human melanoma cell lines to hyperthermia induced cell death." (PMID 27626679, 2016). "In our study, we have shown HSPB1 is a thermosensitive HSP that was dramatically upregulated by hyperthermia of 45°C in the murine B16 melanoma cell line." (PMID 27626679, 2016). "We found that changes in some crucial proteins, such as Hsp60, HspB1, prohibitin, IDH, and UQCRC1, were associated with apoptosis or the mitochondrial function against melanoma cells." (PMID 23880933, 2013). "Interestingly, an increase in HSP27 expression was observed after exposure to a higher temperature in all melanoma cells: HSPB1 (A375 and G-361), and HSPB6 (SK-MEL-1) and HSP40: DNAJC4 (A375, G-361, and SK-MEL-1)." (PMID 37886980, 2023). "We used E. coli bacteria and B16-F10 murine melanoma cells, which both overexpress HSPB1." (PMID 35806322, 2022). "Under standard conditions (37 °C), melanoma cells were characterized by a high level (>0.04) of HSPD1 (HSP60), HSPA8 (HSP70), and HSP90AB1 (HSP90), and a medium level (0.02–0.04) of HSPB1 (HSP27), HSPA9 (HSP70), and AHSA1 (HSP90)." (PMID 37886980, 2023). "Of note, we also checked cBioPortal and found that these proteins related to angiogenesis (i.e. FASN, CLIC4, HSPB1, ARHGEF1, PHGDH, MYO1C, CAV1) are altered in a total of 242 melanoma patients out of a total of 471 (51.36%)." (PMID 31142788, 2019). "In the present study, we identified HSPB1 (HSP27) is hyperthermically inducible or endogenously highly expressed in both murine and human melanoma cell lines." (PMID 27626679, 2016). "Moreover, melanoma patients receiving immune checkpoint blockade (ICB) therapy with high expression of CD24, HSPB1, and SLC25A5 also had a poor prognosis." (PMID 40777020, 2025). "Finally, we confirmed that secretion of C-terminal HSPB1 fragment was significantly inhibited lung and liver tumor progression of B16F10 melanoma cells and lung tumor progression of CT26 colon carcinoma cells, compared to full-length HSPB1." (PMID 24465581, 2014). "The treatment of the 4C11− non-metastatic melanoma cell line with TSA resulted in no significant change of Hspb1 mRNA expression." (PMID 22984562, 2012). "These genes, except for Hspb1, were not previously reported to be modulated by 5AzaCdR treatment in melanoma cells." (PMID 22984562, 2012). "The positive correlation between HSPB1 (heat shock 27 KDa protein 1) and SERPINE1 (serpin peptidase inhibitor, clade E, member 1) overexpression induced reversal of the invasive and metastatic phenotype of melanoma cells in vitro." (PMID 22984562, 2012).
melanoma (continued). "B16F10 melanomas, which do not express HSPB1, were injected into mice to generate lung metastases." (PMID 24465581, 2014). "Curiously, the expression profile exhibited for the genes HSPB1 and SERPINE1 in Mel-2 and Mel-3 human metastases was noted for mouse cell lines representing pre-malignant melanocytes and non-metastatic melanoma cells (4C and 4C11− cell lines, respectively) in comparison to melan-a melanocytes." (PMID 22984562, 2012).
amyotrophic lateral sclerosis (13 papers, 2012 to 2025). Amyotrophic lateral sclerosis (ALS) is a neurodegenerative disease characterized by progressive muscular paralysis reflecting degeneration of motor neurons in the primary motor cortex, corticospinal tracts, brainstem and spinal cord. "Some HSPB1 mutations even associate with a rapidly progressive phenotype that resembles Amyotrophic Lateral Sclerosis (ALS)." (PMID 35281256, 2022). "So far, Seven HSPB1 mutations have been found in seven unrelated patients with sporadic amyotrophic lateral sclerosis (ALS); among them, bulbar symptoms were relatively common (5/7), and cognitive impairment was found in two patients." (PMID 36291591, 2022). "Two mutations in HSPB1 (p.Gln190His and p.Al204Glyfs*6) were reported recently in patients with amyotrophic lateral sclerosis (ALS) phenotype, which suggested overlap of ALS and CMT2F/HMN2B." (PMID 29381233, 2018). "In addition, most mutations in HSPB1 can cause axonal Charcot-Marie-Tooth neuropathy and/or distal hereditary motor neuropathy and sporadic amyotrophic lateral sclerosis (ALS)." (PMID 40385290, 2025). "HspB1 upregulation is reported in an animal model of amyotrophic lateral sclerosis (ALS), with higher expressing HspB1 detected in the nucleus of neurons and glial cells of the spinal cord ventral horn in the early stages, which is localized to reactive glial cells in the later stages." (PMID 40003991, 2025). "In this cohort is reported a patient carrying a novel familial mutation in the tail domain of KIF5A [a protein domain previously associated with familial amyotrophic lateral sclerosis (ALS)], and a CMT patient carrying a HSPB1 mutation, previously reported in ALS." (PMID 34354735, 2021). "In various neurodegenerative diseases, including Alzheimer's disease (AD), PD, multiple sclerosis (MS), amyotrophic lateral sclerosis (ALS) and frontotemporal dementia, Hspb1 has been consistently observed to be upregulated, highlighting its significance as a key molecule of interest 42-46." (PMID 39239519, 2024).